PI15 (peptidase inhibitor 15)
Description:
Serine protease inhibitor which displays weak inhibitory activity against trypsin. May play a role in facial patterning during embryonic development (By similarity).
Synonyms: p25TI; CRISP8; P24TI
Tractability: Antibody: UniProt places it where antibodies can reach, with high confidence; UniProt predicts a signal peptide or a membrane-spanning region; its Gene Ontology location is reachable by antibodies, with medium confidence.
Gene: Protein-coding gene on chromosome 8 (74,824,534 to 74,855,029, forward strand). Ensembl gene ENSG00000137558.
Subcellular location: Secreted
Subcellular location (Human Protein Atlas): Vesicles; Cytosol; Predicted to be secreted
Gene Ontology:
Cellular component: extracellular exosome; extracellular region
Genetic constraint (gnomAD): Loss-of-function variants: 8 observed, 8.84 expected, observed/expected ratio (o/e) 0.91, 90% interval 0.53 to 1.6. That is too few expected variants to judge how well the gene tolerates losing a copy. Missense variants: 126 observed, 159.65 expected, observed/expected ratio (o/e) 0.79, 90% interval 0.68 to 0.92. Synonymous variants: 64 observed, 61.42 expected, observed/expected ratio (o/e) 1.04, 90% interval 0.85 to 1.28.
Homologues: Orthologues: chimpanzee PI15 (100% identical), macaque PI15 (99% identical), rabbit PI15 (99% identical), dog PI15 (98% identical), pig PI15 (98% identical), guinea pig PI15 (96% identical), mouse Pi15 (93% identical), rat Pi15 (91% identical), zebrafish pi15a (74% identical), zebrafish pi15b (70% identical), Caenorhabditis elegans scl-5 (24% identical), Caenorhabditis elegans scl-10 (23% identical), and 42 more. Paralogues in human: R3HDML (54% identical), CRISPLD2 (52% identical), CRISPLD1 (50% identical), GLIPR1 (28% identical), CRISP3 (26% identical), CLEC18A (26% identical), CLEC18C (26% identical), GLIPR1L1 (26% identical), CLEC18B (26% identical), CRISP1 (25% identical), CRISP2 (24% identical), GLIPR1L2 (22% identical), and 1 more.
Diseases named in the same sentence as PI15 in open-access papers:
PI15 is named in the same sentence as 20 diseases in open-access papers, as found by Europe PMC text mining. Sharing a sentence is not in itself a finding about the gene and the disease. The quoted sentences say what the papers report.
cholangiocarcinoma (4 papers, 2020 to 2022). A carcinoma that arises from the intrahepatic biliary tree (intrahepatic cholangiocarcinoma) or from the junction, or adjacent to the junction, of the right and left hepatic ducts (hilar cholangiocarcinoma). "PI15 has been identified as a potential diagnostic marker in colorectal carcinoma and cholangiocarcinoma." (PMID 33644115, 2021). "Among target genes of miR-99a, peptidase inhibitor 15 (PI15) has been reported to act as a novel blood diagnostic marker for cholangiocarcinoma, and the plasma PI15 level in HCC patients was clearly higher than normal." (PMID 33274225, 2020).
breast carcinoma (2 papers, 2021 to 2024). "Thus, PI15 may be also a potential prognostic factor in Her2-subtype breast cancer." (PMID 33644115, 2021). "In the selected key specific DEGs for Her2-subtype breast cancer, the expression of IL21R, IFI30, PI15, FAM189A2, and MYZAP were significantly correlated with the prognostic survival of the patients." (PMID 33644115, 2021). "Our results showed that PI15 was specifically downregulated in the Her2 subtype, and this high expression predicted high RFS in Her2-subtype breast cancer (p < 0.05)." (PMID 33644115, 2021). "IL21R, IFI30, PI15, and FAM189A2 may be involved in recurrence of Her2-subtype breast cancer IFI30, PI15, FAM189A2, and MYZAP can be used as the specific prognostic markers for Her2-subtype breast cancer." (PMID 33644115, 2021).
Chlamydia infection (1 paper, 2018). "Stable knockdown of PI15 in HeLa cells also caused a similar decrease in processed CPAF during Chlamydia infection (see lane 2 vs. 4)." (PMID 29900129, 2018). "We previously observed the loss of the ~55 kDa PI15 isoform during late stages of Chlamydia infection." (PMID 29900129, 2018). "Immunoprecipitation of Flag-tagged PI15 in cells transiently expressing Flag-PI15 using anti-Flag antibodies pulled down the inactive CPAF zymogen during early stages of Chlamydia infection." (PMID 29900129, 2018). "Furthermore, processing of PI15 to a lower molecular weight form depended on the multiplicity of Chlamydia infection (MOI) and increased with increasing MOI." (PMID 29900129, 2018). "Hence, we further analyzed expression dynamics of PI15 in HeLa cells during different time points of Chlamydia infection." (PMID 29900129, 2018). "Interestingly, in cells infected with RST17 (CPAF−) the high-molecular mass forms of PI15 remained uncleaved whereas the low-molecular PI15 forms were strongly reduced in comparison to wild type Chlamydia infected cells, suggesting that CPAF mediates this conversion during Chlamydia infection." (PMID 29900129, 2018).
chlamydial infection (1 paper, 2018). "During a microarray study of host cell transcriptome, we encountered a human peptidase inhibitor called PI15 (also called as p25TI) that was differentially regulated during chlamydial infection." (PMID 29900129, 2018). "We therefore investigated the role of PI15 during chlamydial infection." (PMID 29900129, 2018).
gastric tumor (1 paper, 2023). "The results obtained from reverse transcription-quantitative polymerase chain reaction (RT-qPCR) and immunohistochemical indicated that the expression levels of CGB5, UPK1B, and PI15 were downregulated in gastric tumor cells, while DNAAF3 was upregulated." (PMID 37711621, 2023).
liver cancer (1 paper, 2021). An epithelial or non-epithelial malignant neoplasm that arises from the liver. "We report for the first time that LOC644135, ELN, GULP1, ENSG00000248635, GPM6A, and PI15 are associated with the risk of liver cancer recurrence." (PMID 34956309, 2021).
Obesity (1 paper, 2020). Accumulation of substantial excess body fat. "These genes were also examined in female placentae, however, only Pi15, Nup210, Acta2, Rnf222, and Muc15 were significantly modulated by obesity." (PMID 32203108, 2020).
tumor (5 papers, 2007 to 2025). "Existing evidence indicates PI15 is highly expressed in a variety of tumour tissues and is a trypsin‐binding protein." (PMID 40845143, 2025). "Notably, PI15 is upregulated in multiple tumour types, with significant overexpression in cholangiocarcinoma tissues compared to normal liver controls." (PMID 40845143, 2025). "A decrease in expression level of SNORD114, SFPR1 and PI15 was observed with tumor development." (PMID 30647841, 2018). "Furthermore, we found that a decrease in PI15 (Peptidase inhibitor 15) gene correlated with tumor progression." (PMID 30647841, 2018). "From the RT-qPCR and immunohistochemical, the expression of DNAAF3 was higher in tumor and the expression of PI15, UPK1B, and CGB5 was lower in tumor." (PMID 37711621, 2023). "In comparison, among 16 downregulated genes relative to IQGAP1 under-expression, FAM65B (RIPOR2), PI15, and HDAC9 are downregulated in either iCluster 1, iCluster 2, or both in comparison to the matched non-tumor tissues." (PMID 33498739, 2021). "PI15 (peptidase inhibitor 15) was downregulated, whereas LRRC15 (leucine rich repeat containing 15) was upregulated in both tumor cells." (PMID 17389037, 2007). "Additionally, the investigation of the expression of four signature genes in the tumor immune microenvironment through single-cell sequencing analysis confirmed the presence of CGB5, PI15, UPK1B, and DNAAF3 in the T cell cluster." (PMID 37711621, 2023). "Out of these, SFRP1, PI15 and RELN were downregulated as the tumor progresses toward malignancy." (PMID 30647841, 2018).
infection (1 paper, 2018). The state of being infected such as from the introduction of a foreign agent such as serum, vaccine, antigenic substance or organism. "We suggest here that CPAF utilizes a host cell protein PI15 to initiate its auto-processing during the early stages of infection since silencing of PI15 caused decreased levels of mature CPAF in infected cells." (PMID 29900129, 2018). "Corroborating our results, we detected gradual loss of ~55 kDa forms of PI15 at later infection time points with simultaneous appearance of low-molecular PI15 species after midterm of the chlamydial life cycle, which might represent cleaved PI15 fragments." (PMID 29900129, 2018). "Quantification of chlamydial progeny in secondary infection assays confirmed the inhibition of the development of wild type Chlamydia but not of RST17 (CPAF−) upon PI15 overexpression." (PMID 29900129, 2018). "These assays revealed decreased numbers of chlamydial progeny in absence of PI15, which was quantified by counting the number of chlamydial inclusions during secondary infection and by calculating chlamydial genome equivalents by quantitative PCR." (PMID 29900129, 2018). "Hence potential artificial cleavage of PI15 was verified by simultaneous detection of the uncleaved CPAF in vitro substrate RFX5 that remained intact in lysates collected at different time points post infection." (PMID 29900129, 2018).
PI15 also shares sentences with these, for which no sentence is quoted: cancer (2 papers); lung fibrosis (2); autism (1); chronic bronchitis (1); colorectal carcinoma (1); epilepsy (1); Granuloma (1); prostate carcinoma (1); schizophrenia (1); systemic sclerosis (1); viral infection (1).